APOA1 (apolipoprotein A1)
Diseases named in the same sentence as APOA1 in open-access papers (continued):
Sharing a sentence is not in itself a finding about the gene and the disease.
pneumonia (continued). "In addition, ApoA1/A2/A4 and ApoC3 up-regulated by I.T. LPS were also identified in BALF from pneumonia-associated ARDS patients in a separate study." (PMID 31373289, 2019). "However, the relationship between LDH and apolipoprotein A1 levels in patients with severe pneumonia remains unclear." (PMID 38699695, 2024). "Finally, one hundred years after surrogate sentinel HDL-cholesterol for pneumonia, apolipoprotein-A1 for the second time in a century, could be “one of the early warning systems that alert the world to potential outbreaks”." (PMID 33216772, 2020). "There were significant differences in total protein, globulin, FIB, APTT, TT, HDL-C, apolipoprotein A1 (APOA1), apolipoprotein B (APOB), and lipoprotein between patients with TB and those with pneumonia (P < 0.05)." (PMID 28278182, 2017). "LDH and ApoA1 levels were found to correlate with age, with increased LDH levels and decreased ApoA1 levels in patients older than 70 years with severe pneumonia, which correlated with poorer immune function status and more severe muscle loss in older patients." (PMID 38699695, 2024). "The relationship between severe pneumonia disease and admission LDH and ApoA1." (PMID 38699695, 2024). "Vice versa, overexpression of APOA1 or treatment with reconstituted HDL showed positive effects in animal models of several lung diseases such as acute lung injury, acute respiratory distress syndrome, pneumonia, asthma, chronic obstructive lung disease, pulmonary fibrosis, or pulmonal hypertension." (PMID 35487261, 2022). "The decrease in apolipoprotein-A1 during the peak of the pandemic in April was not so surprising, as very low levels of HDL-cholesterol were already known in severe pneumonia since 1920." (PMID 33216772, 2020).
preeclampsia (8 papers, 2018 to 2025). Preeclampsia is a hypertensive disorder of pregnancy that is characterized by new-onset hypertension with proteinuria presenting after 20 weeks of gestation, and depending on mild or severe forms may initially present with severe headache, visual disturbances, and hyperreflexia. "Patients with different diseases were examined, and it was revealed that there is an elevated level of ApoA1 that can be associated in preeclampsia, endometriosis, PCOS and repeated implantation failure." (PMID 38203658, 2023). "Importantly, we found that the ratio of sFlt1/PLGF was more efficient in predicting the risk of preeclampsia than the level of APOA1." (PMID 38003549, 2023). "A 2023 study demonstrated elevated peripheral APOA1 levels in preeclampsia patients and further established through in vitro experiments that APOA1 significantly inhibits trophoblast proliferation and invasive capacity." (PMID 40778280, 2025). "In this study, we found that APOA1 levels were elevated in both the plasma and placental tissues of patients with preeclampsia." (PMID 38003549, 2023). "To further verify the mechanisms of APOA1 in preeclampsia, we knocked down APOA1 in HTR8/SVneo cells using three different siRNAs." (PMID 38003549, 2023). "In this study, we found that the expression of APOA1 was elevated in both the plasma and placental tissues of patients with preeclampsia." (PMID 38003549, 2023). "The plasma APOA1 level was observed to be significantly elevated in preeclampsia patients." (PMID 40778280, 2025). "Importantly, we detected the concentration of APOA1 using the ELISA assay in normal control women (n = 30) and women with preeclampsia (n = 29) from a prospective cohort study." (PMID 38003549, 2023). "We found that the expression of APOA1 was significantly elevated in the plasma of women with preeclampsia during late gestation but not during early and mid-term gestation." (PMID 38003549, 2023). "Notably, the AUC of the ratio of sFlt1/PLGF during mid-term gestation for predicting preeclampsia was 0.926 (95%CI: 0.862–0.992), while it was not significantly elevated by adding the concentration of APOA1." (PMID 38003549, 2023). "Thus, it is not realistic to use APOA1 as a predictor of preeclampsia onset; however, APOA1 may be useful as a judgment of the severity of the condition, which in turn may help in the treatment of the disease." (PMID 38003549, 2023).
thyroid cancer (8 papers, 2011 to 2024). "In fact, it was found that elevated HDL-C and cholesterol levels, which are regulated by APOA1, were associated with a reduced thyroid cancer risk." (PMID 38067270, 2023). "Meanwhile, the slope of the line for “total cholesterol”, “apolipoprotein B”, and “ratio of apolipoprotein B to apolipoprotein A1”, respectively, was negative, suggesting that an increase of those apolipoprotein led to a reduced risk of thyroid cancer." (PMID 38189054, 2023). "Observing the identified OR values, HDL cholesterol might be the risk factor (OR > 1, p < 0.05) and “total cholesterol”, “apolipoprotein B”, and “ratio of apolipoprotein B to apolipoprotein A1” were the protective factors (OR < 1, p < 0.05) for thyroid cancer." (PMID 38189054, 2023). "As PTC incidences continues to increase, our findings demonstrated a negatively association between PTC and apoA-1 in male PTC patients, which may contribute to further investigation concerning diagnosing and preventing this most common type of thyroid cancer." (PMID 33853556, 2021). "Other contradicting findings stated that APOA1 and APOA4 were overexpressed in PTC, the most prevalent subtype of thyroid cancer, when a proteome analysis was conducted on PTC cells." (PMID 38067270, 2023). "APOA1, APOA2, and APOA4 were found to be downregulated in female patients with thyroid cancer." (PMID 38067270, 2023).
acute lymphoblastic leukemia (7 papers, 2012 to 2025). Leukemia with an acute onset, characterized by the presence of lymphoblasts in the bone marrow and the peripheral blood. "For instance, ApoA1 levels were decreased in children with acute lymphoblastic leukemia and returned to normal after therapy." (PMID 33336932, 2021). "When patients with acute lymphoblastic leukemia (ALL) were treated with induction treatment, dynamic increases in serum HDL-C and ApoA1 predicted better chemotherapy efficacy." (PMID 34544437, 2021).
chronic obstructive pulmonary disease (7 papers, 2012 to 2025). A chronic and progressive lung disorder characterized by the loss of elasticity of the bronchial tree and the air sacs, destruction of the air sacs wall, thickening of the bronchial wall, and mucous accumulation in the bronchial tree. "Apolipoprotein A1 (P02647) could be a biomarker that has been associated with chronic obstructive pulmonary disease (COPD), tuberculosis (TB), and sarcoidosis." (PMID 41279897, 2025). "However, in a study in which patients with chronic obstructive pulmonary disease (COPD) were treated with aerobic exercise, increase in ApoA1 concentration was observed." (PMID 32824020, 2020).
glioma (7 papers, 2014 to 2024). A benign or malignant brain and spinal cord tumor that arises from glial cells (astrocytes, oligodendrocytes, ependymal cells). "A significant increase in apolipoprotein E (APOE) and apolipoprotein A1 (APOA1) protein levels in the CSF of GBM patients has been reported compared to those in the CSF of patients with low-grade gliomas." (PMID 39062515, 2024). "The trends for APOA1 were found to be opposite in Gliomas and Meningiomas, with higher expression in GBMs and Grade I meningiomas as compared to the LGGs and Grade II meningiomas, respectively." (PMID 34055594, 2021). "The expression levels of proteins such as VTN, APOA1 and PTGDS were found to be highly up regulated in GBM as compared to low grade gliomas." (PMID 34055594, 2021). "Our own work identified APOA1 and APOA4 in the proteomic analyses of EVs derived from human medulloblastoma cell lines and murine glioma cells, with APOB and APOE identified in EVs from other tumor cell lines (Graner, unpublished data)." (PMID 34360613, 2021). "Three peptides of 5 Proteins which includes APOA1, APOE, PTGDS, VTN and C3 were monitored for both Meningioma and Glioma samples." (PMID 34055594, 2021). "The same three peptides of APOE and APOA1 gave a cumulative fold change of 1.59 and 2.69 respectively in GBM when compared to low grade glioma." (PMID 34055594, 2021).
lung disease (7 papers, 2016 to 2022). "After correction, it appears that all adjusted P-values for age, gender, smoking status, consumption of alcohol and the presence of pulmonary diseases remained statistically significant except for C3a and ApoA1 that need therefore careful consideration." (PMID 27599571, 2016). "In a murine model of cigarette smoke-induced lung disease, transgenic mice that conditionally over-expressed the human APOA1 gene in alveolar epithelial cells were protected from developing emphysema." (PMID 27708582, 2016).
non-small cell lung carcinoma (7 papers, 2016 to 2026). A group of at least three distinct histological types of lung cancer, including non-small cell squamous cell carcinoma, adenocarcinoma, and large cell carcinoma. "In patients with advanced non-small cell lung cancer, serum ApoA1 levels are associated with the frequency of EGFR T790M mutations and treatment response to EGFR tyrosine kinase inhibitors." (PMID 38212711, 2024). "Another study determined that APOA1 levels were significantly elevated in SCLC, despite not being markedly increased in non-small-cell lung cancer (NSCLC), and found that reduced APOA1 levels correlated with an increased recurrence of SCLC." (PMID 38067270, 2023).
acute respiratory distress syndrome (6 papers, 2013 to 2022). Progressive and life-threatening pulmonary distress in the absence of an underlying pulmonary condition, usually following major trauma or surgery. "The protective role of apoA-1 is also evidenced in acute lung injury and acute respiratory distress syndrome." (PMID 33344516, 2020). "In addition, aside from the new coronavirus, the correlation between APOA1 with acute respiratory distress syndrome and influenza has been noted by previous studies." (PMID 33244380, 2020).
allergic rhinitis (6 papers, 2020 to 2025). Inflammation of the nasal mucous membranes caused by an IgE-mediated response to external allergens. "C3, A2M, APOA1, and APOA2 were also found to be significantly more abundant in nasal mucus in allergic rhinitis patients in our previous studies." (PMID 32266843, 2020).
carotid atherosclerosis (6 papers, 2017 to 2025). A thickening and loss of elasticity of the walls of carotid arteries that occur with formation of atherosclerotic plaques. "Recently, it has been demonstrated that ApoB/ApoA1 ratio is independently associated with carotid atherosclerosis in T2DM patients with controlled LDL-c levels." (PMID 32505210, 2020).
colonic adenocarcinoma (6 papers, 2012 to 2021). "Expression of ApoA1 is associated with colonic adenocarcinoma progression, and thus ApoA1 is a potential marker of the aggression." (PMID 26537097, 2015). "Apoa1 is increased in progressive stages of colonic adenocarcinoma with higher expression in carcinomas than in normal mucosal epithelial cells." (PMID 23226526, 2012). "Besides its roles in the lipid transport, a recent study revealed that APOA1 has an important role in tumour invasion and metastasis in colonic adenocarcinoma." (PMID 26463353, 2016).
diabetic nephropathy (6 papers, 2010 to 2025). "Further, microalbuminuria and diabetic nephropathy patients marked the excretion of Ig kappa chain V–II, protein 25, Ig lambda 2 chain region, Alpha 1 acid glycoprotein 1, Apolipoprotein A1, transthyretin/prealbumin, Ig kappa C chain region, AMBP, Cystatin C, zinc alpha 2 glycoprotein and Ubiquitin." (PMID 31131043, 2019). "Four of the peaks that were discovered have been identified as transthyretin, apolipoprotein A1, apolipoprotein C1 and cystatin C. Several yet unidentified proteins discovered by this novel approach appear to have more potential as biomarkers for diabetic nephropathy." (PMID 20205888, 2010).
endometrial cancer (6 papers, 2019 to 2025). Primary or metastatic malignant neoplasm involving the endometrium (mucous membrane that lines the endometrial cavity). "In our review, three studies demonstrated that APOA1 expression was inversely associated with endometrial cancer, while one study found that higher APOA1 expression was positively associated with the disease." (PMID 39194522, 2024). "Quantification analysis in 36 patients with endometrial cancer compared to 36 healthy individuals confirmed the upregulation of APOA1, HBB, CA1, HBD, LPA, SAA4, PF4V1, and APOE." (PMID 36551747, 2022). "Several blood-based protein biomarker candidates for endometrial cancer detection were suggested, including the Apolipoprotein family (APOA1/4, APOC1/2/3, and APOE), Clusterin (CLU), Inter-alpha-trypsin inhibitor heavy chain (ITIH2 and ITIH4), and Antithrombin III (ATR/SERPINC1)." (PMID 39194522, 2024). "Six of them were upregulated in endometrial cancer patients (CLU, SERPINC1, ITIH4, C1RL, APOC3 and DSC1), while ten were downregulated (APCS, C9, APOA1, ALB, APOA4, CFHR1, ITIH2, and ACTB)." (PMID 39194522, 2024). "Two biomarkers (APOA1 and its modified form) were downregulated, while two (APOC1 and its modified form) were upregulated in endometrial cancer patients; these differences were also significant for stage I patients." (PMID 39194522, 2024).
gout (6 papers, 2016 to 2025). A condition characterized by painful swelling of the joints, which is caused by deposition of urate crystals. "rs670 in the APOA1 gene increases the risk of gout and supports the APOA1 involvement in gouty inflammatory pathways." (PMID 33926105, 2021). "The findings indicate that LDL-C and ApoA1 are improbable mediators of the genetically predicted association between PNPLA3 inhibition and gout." (PMID 40881642, 2025). "New findings include the association between higher levels of omega-6% and an elevated risk of gout, the positive correlations of medium HDL, and ApoA1, with alcohol-related mental and behavioural disorders, and the positive association between alanine/glutamine and T2D." (PMID 40973818, 2025). "Further analysis revealed that PNPLA3 inhibition might elevate TG, LDL-C, and ApoA1 levels, and TG may partially mediate the association between PNPLA3 inhibition and gout." (PMID 40881642, 2025). "APOA1 can bind MSU crystals and/or inhibit IL-1β production, having thus a role in initiation and/or resolution of gout attacks." (PMID 33926105, 2021). "Subsequently, we confirmed whether TG, LDL-C, and ApoA1 played roles in the genetically predicted link between PNPLA3 inhibition and gout." (PMID 40881642, 2025).
hyperuricemia (6 papers, 2016 to 2024). An abnormally high level of uric acid. "Among them, ESR1 has the most frequent gene connections (D = 36), followed by ALB (D = 24) and APOA1 (D = 11), indicating their key roles in both hyperuricemia and HFrEF." (PMID 35911515, 2022).
inflammatory bowel disease (6 papers, 2014 to 2023). A spectrum of small and large bowel inflammatory diseases of unknown etiology. "Importantly, deficiency in human APOA1 expression has been linked to susceptibility to inflammatory bowel disease in humans." (PMID 29066772, 2017).
renal cell carcinoma (6 papers, 2015 to 2024). "A similar scenario was published earlier in China, where APOA1 −75 G>A was shown to be associated with risk for the development of renal cell carcinoma." (PMID 34440141, 2021). "More studies of APOA1 stimulators, such as apabetalone, to treat renal cell cancer are warranted." (PMID 35858961, 2022). "Furthermore, ApoA1 presence has been reported within vascular smooth muscle cells, adventitial fibroblasts, and renal cell carcinoma cells, cell types that likely do not synthesize ApoA1, suggesting that some cells can take up and accumulate ApoA1." (PMID 31779197, 2019).
acne (5 papers, 2018 to 2025). An inflammatory process of the sebaceous glands which is characterized by comedones, nodules, papules and/or pustules on the skin. "Studies have shown that APOA1 levels are significantly reduced in acne patients." (PMID 32602849, 2020). "Our data show that azelaic acid, SELL (Leukocyte-Endothelial Cell Adhesion Molecule 1), APOA1 (Apolipoprotein A1) and RBP4 (Retinol Binding Protein 4) are the drivers of seasonal responses contributing to acne pathophysiology." (PMID 33004787, 2020). "However, there is no obvious linear trend relationship between MAP and acne score, ApoA1, FT, FSH and E2 (P-trend > 0.05 for all)." (PMID 41040863, 2025).
acute pancreatitis (5 papers, 2015 to 2022). An acute inflammatory process that leads to necrosis of the pancreatic parenchyma. "The current study was undertaken to investigate the polymorphic sites in the PON1 gene (rs662) and APOA1 gene (rs670 and rs5069) in individuals suffering from acute pancreatitis, from which data was hitherto not available." (PMID 36360205, 2022).
arteriosclerosis (5 papers, 2017 to 2025). A vascular disorder characterized by thickening and hardening of the walls of the arteries. "Both ApoA-1 and HDL-C suppress the progression of arteriosclerosis by binding to excess cholesterol in the periphery and transporting it to the liver." (PMID 37165443, 2023). "However, combination therapy improved the apoB/apoA1 ratio and increased serum adiponectin levels, suggesting that long-term combined administration of vildagliptin and metformin may have an inhibitory effect on arteriosclerosis." (PMID 29017497, 2017).
bipolar disorder (5 papers, 2010 to 2025). A disorder of the brain that causes unusual shifts in mood, energy, activity levels and the ability to carry out day-to-day tasks. "ApoA1 (a major component of high-density lipoprotein (HDL)) and ApoB (a major component of low-density lipoprotein (LDL)) are thought to be involved in the inflammatory processes and neuroprogression associated with bipolar disorder." (PMID 41220462, 2025). "In terms of metabolic indicators, patients with bipolar disorder and comorbid MAFLD showed significantly higher levels of glucose, ALT, ALP, TC, ApoB, triglycerides, and GGT, while exhibiting slightly lower levels of ApoA1 and significantly lower levels of HDL." (PMID 40810071, 2025).
Brain atrophy (5 papers, 2012 to 2025). Partial or complete wasting (loss) of brain tissue that was once present. "It was reported that apolipoprotein A1 possessed the ability to reduce the accumulation of Aβ, mitigated associated toxicity, prevented brain atrophy, and protected cognitive function." (PMID 38515521, 2024). "Lower ApoA1 levels showed a weak but not significant association with an increase in brain atrophy (β = −0.15, p = 0.09)." (PMID 22701550, 2012).
cardiac amyloidosis (5 papers, 2012 to 2026). Cardiac amyloidosis is a condition whereby cardiac tissue is infiltrated by amyloid fibrils. "Here, we report a 69-year-old man with sporadic cardiac amyloidosis who was born to consanguineous parents and carried a homozygous variant of p.Leu202Arg in APOA1." (PMID 39152105, 2024).